API5 (apoptosis inhibitor 5)
Diseases named in the same sentence as API5 in open-access papers (continued):
Sharing a sentence is not in itself a finding about the gene and the disease.
cancer (17 papers, 2012 to 2025). A tumor composed of atypical neoplastic, often pleomorphic cells that invade other tissues. "Overexpression of API5, which encodes an apoptosis inhibitory protein, is related to poor prognosis in various cancers." (PMID 26840027, 2016). "The anti-apoptosis gene API5 down-regulation linked to increase in the survival and resistance cancer cells to chemotherapy." (PMID 23122428, 2012). "Interestingly, vaccination with API5-activated DCs pulsed with antigenic peptides induced antigen-specific T-cell immunity in mice associated with strong antitumor efficacy in both cancer prevention and therapeutic settings." (PMID 38275765, 2024). "Reduced and low levels of Api5 are associated with the increase in cell death in various cancers." (PMID 34385547, 2021). "Notably, expression of API5 was positively associated with the expression of pERK1/2 in both cancer (P < 0.001) and high grade CIN specimens (P = 0.031)." (PMID 25070070, 2014). "As an anti-apoptotic protein, API5 may be closely implicated in the regulation of apoptosis and is highlighted as a potential drug target in cancer." (PMID 25070070, 2014). "API5 acts as a scaffold protein, operating with multiple partners through protein–protein interactions (PPIs) that promote and support cancer cells’ pathological state." (PMID 38275765, 2024). "This review aims to shed light on the multifaceted functions and regulatory mechanisms of API5 in cell fate decisions as well as its interest as therapeutic target in cancer." (PMID 38275765, 2024). "API5 is a cornerstone of these tumoral phenotypes as it is involved in cancer cells’ survival, growth, metastasis, immune silencing, and resistance to chemotherapies, which represent excellent therapeutic targets." (PMID 38275765, 2024). "Combined, these data demonstrate a crucial role for API5 in cancer cell development and progression, providing a rationale for the therapeutic targeting of API5 for cancer treatment." (PMID 38275765, 2024). "Of note, the human API5 gene is located in chromosomal segment 11p12-13, in a region that is amplified in a number of cancers." (PMID 38275765, 2024). "API5’s intricate involvement in these critical cellular processes underscores its significance in both health and disease, particularly in cancer biology." (PMID 38275765, 2024). "As such, the therapeutic inactivation of API5 functions for anti-cancer therapies is attractive, with recent work on API5 inhibitors identifying compounds to target its cellular functions." (PMID 38275765, 2024). "Api5 has been found to be overexpressed in different types of cancers like cervical, urinary bladder, lung, ovarian and oesophageal cancers." (PMID 34385547, 2021). "Recent studies have suggested that API5 is important for cell cycle progression, immune escape, metastasis, and the stem-cell-like properties of cancer cells and that it promotes drug resistance in cancers." (PMID 32383752, 2020). "In a previous study, anti-API-5 peptide was shown to penetrate the membrane of cancer cells because of the presence of API-5 partner-interacting protein." (PMID 31762939, 2019). "The estrogen receptor alpha (ERα) co-immunoprecipitated with endogenous Api5 (middle) in the cancer cell line MCF-7 that constitutively expresses endogenous ERα." (PMID 28881748, 2017). "Taken together, these results indicate that API5 expression is necessary for maintenance of CSC-like properties in multiple human cancer cells." (PMID 28092370, 2017). "Api5 (Apoptosis inhibitor 5) is an anti-apoptotic factor that confers resistance to genotoxic stress in human cancer." (PMID 28881748, 2017). "We next wanted to further characterize Api5 function in cancer progression by performing a cell migration assay." (PMID 28881748, 2017).
cancer (continued). "Recently, we reported that API5 acts as an immune escape factor, which has a significant role in controlling immune resistance to antigen-specific T cells both in the mouse immune-resistant model and human cancer cells, but its functional association with CSC-like properties remains largely unknown." (PMID 28092370, 2017). "Taken together, these results suggest that API5 confers CSC-like property in cancer cells through the FGF2-NANOG molecular axis." (PMID 28092370, 2017). "Regarding cancer cell differentiation, we observed that higher API5 protein expression in poorly differentiated carcinomas (mean score = 6.62) than in well and moderately differentiated carcinomas (mean score = 4.69)." (PMID 25070070, 2014). "In agreement with this study, we observed that API5 expression levels were positively associated with ERK1/2 phosphorylation both in high grade CIN and cancer specimens." (PMID 25070070, 2014). "Recently, Koci and colleagues analyzed API5 protein expression in a variety of human carcinomas by western blotting." (PMID 25070070, 2014). "Therefore, RT53 and RT39 peptides’ anti-cancer action stems from both their ability to prevent API5 biological functions, through protein–protein interaction inhibition, and through their oncolytic properties." (PMID 38275765, 2024). "An expression analysis of API5 revealed an ubiquitous but varying expression of API5 in cancers." (PMID 38275765, 2024). "Recent data indicate that API5, a multifunctional regulator of cell fate, clearly constitutes a protein of significant interest due to its crucial roles in cancer cells’ vital cellular processes, including, but far from being limited to, resistance to apoptosis." (PMID 38275765, 2024). "Therefore, it is possible that API5 contributes to cancer metastasis through β-catenin- and ERK-mediated MMPs expression." (PMID 38275765, 2024). "Indeed, a clear correlation between API5 and FGF-2 expression was observed in an array of cancer cells, and forced expression or siRNA-mediated inhibition of API5 resulted in concomitant FGF-2 expression increase or decrease, respectively." (PMID 38275765, 2024). "This indicates that the heptad leucine repeat region of API5 could constitute a therapeutic target for anti-cancer drugs." (PMID 38275765, 2024). "While its biological functions are far from being completely understood, numerous data clearly indicate that API5 has great potential as an intervention target for the novel treatment of refractory cancers, and its targeting can hence be regarded as a promising strategy in drug discovery." (PMID 38275765, 2024). "Apoptosis inhibitor 5 (Api5), an inhibitor of apoptosis, is upregulated in cancers." (PMID 37095445, 2023). "It has also been reported that Api5 is overexpressed in many cancers." (PMID 34385547, 2021). "Thus inhibitors of p300 and inducers of HDAC1 have therapeutic implications in the treatment of cancers that have high expression of Api5." (PMID 34385547, 2021). "High levels of Api5 provide cancer cells the ability to evade immune response mediated cell death." (PMID 34385547, 2021). "Moreover, by comparing the 13 survival-related gene lists, seven genes (SLK, API5, BTBD2, PTAR1, VPS37A, EIF2B1, and ZRANB1) were found to be associated with prognosis in a variety of cancers." (PMID 32300588, 2020). "As FGF2-FGFR1 signaling is critical for API5-mediated phenotypes of cancer cells, we reasoned that inhibition of FGFR1 signaling may serve as an effective strategy for targeting cancer cells, which highly express API5." (PMID 28092370, 2017). "Furthermore, a study by Ahel and collaborators, showed that Api5 interacts with the chromatin remodeling enzyme ALC1 (Amplified in Liver Cancer 1) which is a member of the SNF2 (Sucrose Non Fermenting 2) family." (PMID 23940755, 2013).
cancer (continued). "Moreover, the peptides demonstrated potent pro-apoptotic activity and synergy with anticancer drugs, as well as anti-migration potential, on multiple cancer cell lines as well as primary cutaneous T-cell lymphoma (Sézary syndrome) cells, thus phenocopying the consequences of API5 silencing." (PMID 38275765, 2024). "Importantly, the API5/FGFR1/ERK/BIM axis appears to be conserved in multiple cancers." (PMID 38275765, 2024). "Therefore, controlling ERK activity as well as BIM cellular levels by means of API5 targeting might open new therapeutic options for the treatment of aggressive, chemo-refractory cancers." (PMID 38275765, 2024). "Finally, our findings propose that the blockade of FGFR signaling may be a promising therapeutic approach for cancer, especially if there is high API5 expression." (PMID 28092370, 2017). "Consequently, the steady-state API5 acetylation–methylation equilibrium, which functions as a molecular rheostat governing API5 stability and antiapoptotic properties, might be amenable to therapeutic exploitation as an anti-cancer strategy." (PMID 38275765, 2024). "API5 (APoptosis Inhibitor 5) and nuclear FGF2 (Fibroblast Growth Factor 2) are upregulated in various human cancers and are correlated with poor prognosis." (PMID 32383752, 2020). "Although these observations need to be confirmed using primary samples, they fit well with previous data indicating that cancer cells with high levels of AKT/ERK exhibit suppressed BIM expression, and they identify API5 as an immune-related prognostic biomarker." (PMID 38275765, 2024). "Our results provide new insight into the molecular function and mechanism of API5 and nuclear FGF2 as novel components of the mRNA export machineries and suggest a new therapeutic opportunity for the regulation of oncogenic gene expression in cancers." (PMID 32383752, 2020). "As FGF2-FGFR signaling has been implicated as a central channel in the development of CSC-like phenotypes by API5, we believe that inhibition of FGFR signaling may be an effective strategy to control human cancer." (PMID 28092370, 2017). "Identifying whether Api5-induced partial EMT could drive drug resistance and induce stemness characteristics in cancer cells will aid in developing treatment strategies against chemo-resistant cancers." (PMID 37095445, 2023).
infection (5 papers, 2009 to 2023). The state of being infected such as from the introduction of a foreign agent such as serum, vaccine, antigenic substance or organism. "For example, apoptosis inhibitor 5 (API5) is recruited to the VFs as a client during infection, and the interaction between VP3 and API5 was observed to reduce API5 SUMOylation, by inducing UBC9 degradation." (PMID 37239817, 2023). "The results revealed that the apoptotic rate of hemocytes were significantly increased when API5 was silenced during WSSV infection." (PMID 38143869, 2023). "Previous study in our laboratory showed that endogenous API5 colocalizes with VP3 in cytoplasm during infection." (PMID 34372697, 2021). "At 16 h post infection (p.i.), cells were collected and lysates were subjected to immunoprecipitation using antibodies specific for NP and API5." (PMID 26673663, 2015). "In the present study, we elucidate how NP of IAV interact with and manipulate a host inhibitor of apoptosis API5 during infection, and in the process stimulating E2F1-dependent apoptotic pathway." (PMID 26673663, 2015). "Having assessed the effect of API5 on E2F1-dependent transactivation of proapoptotic genes under conditions of infection, we next set out to investigate its impact on the process of apoptosis itself." (PMID 26673663, 2015). "Second, cells transfected with either control or API5 (API5-Flag) expression construct followed by infection with PR8 strain." (PMID 26673663, 2015). "Essentially, API5 downregulates APAF1 and prevents activation of caspases, thus impeding apoptosome formation under infection conditions." (PMID 26673663, 2015). "On the host side, 4 genes were upregulated in response to infection with the Δlpp mutant but not WT Y. pestis, including apoptosis inhibitor 5 (Api5), which suggests that Lpp might influence the host apoptotic response to infection and is consistent with our recently published data." (PMID 20145715, 2009).
adenocarcinoma (1 paper, 2017). A common cancer characterized by the presence of malignant glandular cells. "Furthermore, to assess the role of Api5 in the development of adenocarcinoma, we evaluated several parameters, first in vitro." (PMID 28881748, 2017).
cardiovascular disease (1 paper, 2022). "Published evidence for a role for API5 in human cardiovascular disease is limited to reports of a potential involvement in vascular endothelial cell apoptosis." (PMID 35548346, 2022). "The data generated from both the human in silico and zebrafish in vivo assessments undertaken supports further investigation of the potential roles of API5, HSPB7, and LMO2 in human cardiovascular disease." (PMID 35548346, 2022).
kidney diseases (1 paper, 2024). "Literature searches have shown that no studies are showing the relationship between API5 protein and kidney diseases." (PMID 39895822, 2024).
API5 also shares sentences with these, for which no sentence is quoted: dilated cardiomyopathies (2 papers); prostate carcinoma (2); alopecia (1); cardiomyopathy (1); cervical intraepithelial neoplasia (1); cervical tumor (1); gastric cancer (1); invasive breast carcinoma (1); myocardial infarction (1); prostatic adenocarcinomas (1); scoliosis (1); Sézary syndrome (1); triple-negative breast carcinoma (1).